EGFR (epidermal growth factor receptor)
Diseases named in the same sentence as EGFR in open-access papers (continued):
Sharing a sentence is not in itself a finding about the gene and the disease.
non-small cell lung carcinoma (continued). "This led the European Commission to approve Amivantamab, in combination with chemotherapy, as the first-line treatment for advanced non-small-cell lung cancer with activating EGFR exon 20 insertion mutations." (PMID 40943615, 2025). "Epidermal growth factor receptor (EGFR) tyrosine kinase inhibitor (TKI)-based combination therapy modalities for patients with EGFR-mutated stage IV non-small cell lung cancer (NSCLC) are being investigated." (PMID 41383503, 2025). "The first-generation reversible EGFR-TKIs, gefitinib and erlotinib, have shown benefits in non-small cell lung cancer (NSCLC) patients carrying EGFR-sensitizing mutations (L858R in exon 21 and exon 19 deletions)." (PMID 40283927, 2025). "FASN-mediated palmitoylation of target proteins is recognized as a significant mechanism underlying resistance, particularly in TKI-resistant, epidermal growth factor receptor (EGFR)-mutated non-small cell lung cancer." (PMID 40149597, 2025). "Gefitinib and erlotinib are the first-generation anti-EGFR TKIs that were first studied in advanced non-small cell lung cancer and later, for the first time, outperformed chemotherapy in the first-line treatment of EGFR-mutated NSCLC." (PMID 40361442, 2025). "In any case, we must stress that screening for EGFR mutations in early-stage non-small cell lung cancer is merely the first step toward improving patient care." (PMID 40075579, 2025). "EGFR is commonly overexpressed or mutated in many cancers, including non-small-cell lung cancer, colorectal cancer, glioblastoma, and breast cancer, where it promotes oncogenic signaling pathways that facilitate cancer cell proliferation." (PMID 39996991, 2025). "The FLAURA2 and MARIPOSA studies demonstrated that novel combination therapies confer significant clinical benefits in patients with EGFR mutated non-small-cell lung cancer (NSCLC)." (PMID 40647500, 2025). "The emergence of the C797S mutation in the epidermal growth factor receptor (EGFR) significantly limits the efficacy of covalent inhibitors in treating non-small cell lung cancer (NSCLC)." (PMID 40356751, 2025). "Alterations in EGFR, either through gene amplification or mutation, are frequently observed in several malignancies, most notably in non-small-cell lung carcinoma (NSCLC), breast cancer, and colorectal cancer." (PMID 41155588, 2025). "The treatment landscape for EGFR-mutated metastatic non-small cell lung cancer (mNSCLC) has evolved significantly with multiple combination regimens demonstrating superiority over single agent Osimertinib over the past two years." (PMID 40862817, 2025). "Correlation of distribution characteristics and dynamic changes of gut microbiota with the efficacy of immunotherapy in EGFR-mutated non-small cell lung cancer." (PMID 41472726, 2025). "The seminal identification of epidermal growth factor receptor (EGFR) mutations as pivotal oncogenic drivers in non-small cell lung cancer (NSCLC) has catalyzed the evolution of biomarker-guided therapeutic paradigms for advanced disease." (PMID 40322930, 2025). "We here report a case of metastatic epidermal growth factor receptor (EGFR) mutation-positive non-small cell lung cancer (NSCLC) complicated by PTTM, which progressed to acute right ventricular failure and hemodynamic collapse." (PMID 41348429, 2025). "The treatment landscape for advanced non-small cell lung cancer (NSCLC) with common EGFR mutations has evolved significantly, with osimertinib established as the first-line standard." (PMID 41174254, 2025). "Oncogenic mutations of EGFR gene are frequent in non-small cell lung cancer, and KIT or PDGFRA activating alterations are a hallmark of gastrointestinal stromal tumors." (PMID 40514442, 2025). "This study aimed to develop and validate radiomics-based nomograms for the identification of EGFR mutations in non-small cell lung cancer (NSCLC)." (PMID 40242240, 2025).
non-small cell lung carcinoma (continued). "Among these, mutations in the epidermal growth factor receptor (EGFR) gene are a key driver of non-small-cell lung cancer (NSCLC) pathogenesis and progression." (PMID 41156384, 2025). "Although comprehensive genetic analyses of EC have been conducted, driver gene mutations, such as EGFR mutations in non-small cell lung cancer, are yet to be identified, and cytotoxic anticancer drugs remain the key drugs." (PMID 40199194, 2025). "The top 10 most frequent keywords related to tumor microenvironment in non-small cell lung cancer with epidermal growth factor receptor mutation." (PMID 40181972, 2025). "Metabolic reprogramming driven by oncogenic alterations—particularly Epidermal Growth Factor Receptor (EGFR) mutations in non-small cell lung cancer (NSCLC)—creates distinctive plasma signatures with clinical relevance." (PMID 41142757, 2025). "For patients with advanced EGFR-mutated non-small cell lung cancer, EGFR tyrosine kinase inhibitors (EGFR-TKIs) are the preferred treatment option; however, acquired resistance to TKIs is inevitable." (PMID 42004224, 2025). "Previous studies have reported that EGFR and ALK double mutations have been found in the minority of patients with non-small-cell lung cancer, in which patients with double mutations have shorter OS values than patients with EGFR or ALK single mutations." (PMID 40236629, 2025). "In non-small cell lung cancer, a novel 4′-brominated derivative of fisetin inhibits the EGFR/ERK1/2/STAT3 pathways and causes cell cycle arrest and apoptosis without having any negative effects on mice." (PMID 40728967, 2025). "Highly expressed programmed death-ligand 1 (PD-L1) has been associated with poor clinical outcomes in patients with epidermal growth factor receptor (EGFR)-mutated non-small cell lung cancer (NSCLC) receiving EGFR-tyrosine kinase inhibitors (TKIs)." (PMID 41446744, 2025). "A combined therapy comprising HER2 and EGFR inhibitors and HSP90 inhibitors showed improved therapeutic efficacy and the possibility of overcoming resistance in some cancers, but showed a limited effect in EGFR-mutated non-small cell lung cancer (NSCLC)." (PMID 40872476, 2025). "ERLO is employed for the treatment of EGFR mutation-positive Non-Small Cell Lung Cancer (NSCLC) and Pancreas Cancer (in combination with gemcitabine)." (PMID 40745380, 2025). "In advanced non-small cell lung cancer with EGFR mutations, third-generation EGFR TKIs (3rd-G TKIs) are currently the preferred first-line treatment." (PMID 40894225, 2025). "The use of third-generation different tyrosine kinase inhibitors (TKIs) is considered the most effective option for treating advanced non-small cell lung cancer (aNSCLC) with epidermal growth factor receptor (EGFR) mutations." (PMID 40918464, 2025). "Activating epidermal growth factor receptor (EGFR) mutations exon 19 deletions (ex19del) and exon 21 L858R mutations make up 85%–90% of non-small cell lung cancer (NSCLC) cases." (PMID 41282608, 2025). "Central nervous system metastases involving the brain parenchyma and leptomeninges are common in non-small cell lung cancer, especially cases with EGFR mutations." (PMID 40805138, 2025). "For example, activating EGFR mutations in non-small-cell lung cancer predict robust responses to EGFR inhibitors, whereas tumors with KRAS mutations are typically resistant." (PMID 41295218, 2025). "Non-small cell lung cancer harboring EGFR mutations is responsive to targeted therapies such as Osimertinib." (PMID 40740944, 2025). "Epidermal growth factor receptor (EGFR) mutation is the most common driver gene mutation in non-small cell lung cancer (NSCLC)." (PMID 40959071, 2025). "Amivantamab (EGFR×MET), a KIH-based BsAb, has shown efficacy in non-small-cell lung cancer (NSCLC) with EGFR mutations and MET amplification by inhibiting both pathways." (PMID 41154706, 2025).
non-small cell lung carcinoma (continued). "Afatinib and osimertinib are current treatment options for non-small cell lung cancer (NSCLC) patients with uncommon epidermal growth factor receptor (EGFR) mutations, although their efficacy is limited." (PMID 40940797, 2025). "Epidermal growth factor receptor (EGFR) TKIs have become first-line treatment options for advanced EGFR mutation-positive non-small-cell lung cancer (NSCLC)." (PMID 40460109, 2025). "As another example, CT-derived radiomic features have been linked to the epidermal growth factor receptor (EGFR) mutation status in non-small-cell lung cancer (NSCLC), offering a non-invasive method to infer the genome." (PMID 41393619, 2025). "Transformation to small cell lung cancer (SCLC) is a resistance mechanism in epidermal growth factor receptor (EGFR)-mutated non-small cell lung cancer (NSCLC) after EGFR-tyrosine kinase inhibitor (EGFR-TKI) treatment." (PMID 41001033, 2025). "The second of these two tests to be PMA approved by the FDA in 2016 was the cobas® EGFR Mutation Test by Roche Diagnostics, which analyses the mutations in the EGFR gene in patient plasma samples, and is a companion diagnostic for non-small-cell lung cancer." (PMID 41153261, 2025). "Epidermal growth factor receptor (EGFR) is a well-studied oncogene with mutations commonly found in non-small cell lung cancer (NSCLC), one of the primary cancers known to cause spinal metastasis." (PMID 40868304, 2025). "Treatment resistance due to gene alterations remains a challenge for patients with EGFR-mutated advanced or metastatic non-small-cell lung cancer (a/mNSCLC)." (PMID 40277748, 2025). "We searched the Web of Science Core Collection database to select the articles related to tumor microenvironment in non-small cell lung cancer with epidermal growth factor receptor mutation." (PMID 40181972, 2025). "The prognosis of non-small cell lung cancer with common EGFR mutations remains poor, despite the results obtained with the introduction of tyrosine kinase inhibitors." (PMID 40361442, 2025). "A prime example of acquired resistance in EGFR is the well-studied gatekeeper mutation T790M in non-small-cell lung cancer (NSCLC)." (PMID 41018114, 2025). "Amivantamab is an EGFR-MET bispecific antibody with immune cell-directing activity and is FDA-approved for 4 indications in EGFR-mutated advanced non-small cell lung cancer." (PMID 41463160, 2025). "Osimertinib-induced interstitial lung disease in untreated EGFR-mutated, advanced non-small cell lung cancer is being reported at a higher rate in Japan than elsewhere." (PMID 39703157, 2025). "The identification of epidermal growth factor receptor (EGFR) tyrosine kinase (TK) domain mutations in non-small cell lung cancer (NSCLC) patients is crucial for therapeutic decision-making and monitoring EGFR-tyrosine kinase inhibitor (TKI) resistance." (PMID 40510243, 2025). "Epidermal growth factor receptor tyrosine kinase inhibitors (EGFR-TKIs) are the standard first-line therapy for patients with non-small-cell lung cancer (NSCLC) harboring EGFR-activating mutations." (PMID 40136696, 2025). "Of the patients with non-small cell lung cancer, 2 out of 27 had targeted mutations like EGFR (n = 1) or ALK (n = 1) mutations and 15 tumors were PD-L1 positive." (PMID 39651456, 2025). "Ero1a (endoplasmic reticulum reductase 1 alpha) is a negative prognostic marker in a variety of tumor types, including in EGFR-mutated forms of non-small cell lung cancer, colon cancer, and hepatocellular carcinoma." (PMID 41009560, 2025). "Mobocertinib is an oral, irreversible TKI targeting EGFR exon 20 insertion mutations, a subset of non-small-cell lung cancer (NSCLC) with poor response to standard EGFR TKIs." (PMID 41041285, 2025). "EGFR antibodies, such as cetuximab, demonstrate superior clinical efficacy in colorectal cancer (CRC) compared to EGFR-TKIs, which are primarily used in non-small cell lung cancer (NSCLC) with activating EGFR kinase domain mutations." (PMID 40058234, 2025).
non-small cell lung carcinoma (continued). "This study looked at real-world data from patients with advanced or metastatic non-small-cell lung cancer who had a specific genetic change called an EGFR mutation." (PMID 40862783, 2025). "Consistent with this assertion, EGFR has a known GOF mutation (EGFR H773L) in this position that eliminates hydrogen-bonding and has been shown to be sensitive to EGFR kinase inhibitors in non-small cell lung cancer." (PMID 40831936, 2025). "The use of osimertinib after chemoradiotherapy in patients with stage III EGFR-mutated non-small cell lung cancer showed a significant improvement in progression free survival (PFS)." (PMID 40650316, 2025). "Three-year adjuvant treatment with osimertinib improves disease-free survival (DFS) and overall survival (OS) and reduces central nervous system (CNS) recurrence in patients with EGFR-mutated non-small cell lung cancer resection at stage IB–IIIA." (PMID 40650316, 2025). "The two most common and mutually exclusive driver mutations in non-small cell lung cancer affect EGFR and KRAS oncogenes." (PMID 40524071, 2025). "Respiratory system research emphasizes non-small cell lung cancer, particularly EGFR gene mutations." (PMID 40038813, 2025). "The co-administration of osimertinib (an EGFR inhibitor) and T-DM1 facilitates the enhancement of antitumor effects, and T-DM1 can overcome osimertinib resistance in an EGFR-mutated non-small-cell lung cancer model." (PMID 40181988, 2025). "In non-small-cell lung cancer cells with overexpressed or mutated EGFR, HSPA5 is readily located within the nucleus, where it transcriptionally activates the EGFR promoter by binding to the transcriptional suppressor ID2." (PMID 41301006, 2025). "Apigenin and gefitinib’s combined effects on non-small cell lung cancer with a mutated epidermal growth factor receptor (EGFR) were assessed." (PMID 40728967, 2025). "The availability of EGFR-targeted tyrosine kinase inhibitors (TKIs) has increased the survival of non-small cell lung cancer patients harboring EGFR mutations." (PMID 41514577, 2025). "Somatic mutations in EGFR occur in 10–50% of non-small cell lung cancers (NSCLC), varying from 10–15% in Caucasians to 30–50% in East Asian populations." (PMID 39747003, 2025). "Studies have shown that β-Elemene can enhance the sensitivity of EGFR-mutated non-small cell lung cancer to erlotinib by upregulating lncRNA H19 and inducing ferroptosis, providing a new approach to overcoming drug resistance in TNBC." (PMID 40454580, 2025). "A total of 227 articles related to non-small cell lung cancer with concomitant EGFR mutations and its tumor microenvironment were searched in the last decade." (PMID 40181972, 2025). "In 2004, an article on mutations in the EGFR underlying the responsiveness of non-small cell lung cancer to gefitinib was published in the New England Journal of Medicine." (PMID 40136350, 2025). "Epidermal growth factor receptor (EGFR) gene mutations are the most common oncogenic-genomic driver in non-small cell lung cancer (NSCLC), with highest prevalence (30%-50%) in Asian patients." (PMID 40978050, 2025). "Patients with EGFR-mutated non-small cell lung cancer who began osimertinib therapy between September 2018 and August 2020 were enrolled and followed until August 2022." (PMID 39703157, 2025). "One of the reported causes of HES is osimertinib, a main therapy for metastatic EGFR-positive non-small cell lung cancer." (PMID 41376808, 2025). "Amivantamab, a bispecific antibody against epidermal growth factor receptor and mesenchymal-epithelial transition receptors, has been approved for certain types of non-small cell lung cancer; however, it is known to cause severe adverse events." (PMID 41445798, 2025). "The combination of lazertinib and amivantamab has shown superior efficacy over first line osimertinib in EGFR-mutated metastatic non-small cell lung cancer, but is associated with significant toxicity and high costs." (PMID 41198911, 2025).
non-small cell lung carcinoma (continued). "Here, we examine treatment options for EGFR-mutated non-small cell lung cancer patients with central nervous system metastases, highlighting the efficacy of third-generation EGFR-targeted tyrosine kinase inhibitors." (PMID 40805138, 2025). "Epidermal growth factor receptor (EGFR) exon 20 mutations represent a rare subset of genetic alterations in non-small cell lung cancer (NSCLC)." (PMID 40640099, 2025). "In other malignancies, such as EGFR T790M in non-small cell lung cancer or c-KIT secondary mutations in gastrointestinal stromal tumors, this has already translated into routine clinical practice." (PMID 40585845, 2025). "TKIs have dramatically changed the clinical prospects of patients with non-small cell lung cancer harboring EGFR-activating mutations." (PMID 41383506, 2025). "Epidermal growth factor receptor (EGFR) gene-activating mutations were first identified in non-small cell lung cancer (NSCLC) in 2004." (PMID 40361442, 2025). "The top 10 authors and co-cited authors about tumor microenvironment in non-small cell lung cancer with epidermal growth factor receptor mutation." (PMID 40181972, 2025). "In 2003, the FDA approved gefitinib as the first-line treatment for patients with EGFR mutation-positive advanced non-small cell lung cancer (NSCLC)." (PMID 40864738, 2025). "Mutation in the epidermal growth factor receptor (EGFR) results in increased ferroptosis sensitivity in mammary epithelial cells and non-small-cell lung cancers." (PMID 41516092, 2025). "Gefitinib (GEF), a first-generation epidermal growth factor receptor (EGFR) tyrosine kinase inhibitor (TKI) for non-small cell lung cancer (NSCLC), is frequently associated with drug-induced liver injury (DILI), thereby limiting its clinical application." (PMID 40932871, 2025). "Abnormal activation of the EGFR is associated with poor outcomes in various malignancies, including non-small cell lung cancer (NSCLC), breast cancer, neck and carcinoma." (PMID 40445424, 2025). "A well-known example is the treatment of non-small cell lung cancer (NSCLC) in patients with EGFR mutations." (PMID 39757310, 2025). "Non-small cell lung cancer (NSCLC) affects 10-50% of patients with epidermal growth factor receptor (EGFR) mutations." (PMID 39887892, 2025). "Mutations in BRAF V600E and EGFR T790M significantly influence tumor progression and resistance to treatment, particularly in non-small cell lung cancer and colorectal cancer." (PMID 40283283, 2025). "In Asian populations, approximately 50–60% of non-small cell lung cancer (NSCLC) patients harbor EGFR mutations." (PMID 40723259, 2025). "Epidermal growth factor receptor tyrosine kinase inhibitors (EGFR-TKIs) are the standard of care for patients with EGFR-mutated non-small cell lung cancer (NSCLC), and most patients achieve tumor shrinkage." (PMID 41001033, 2025). "Mutations in the epidermal growth factor receptor (EGFR) gene are the most frequent driver mutations in non-small cell lung cancer (NSCLC), especially in patients with East-Asian ethnicity and no history of smoking." (PMID 40940797, 2025). "Osimertinib is the first-line therapy for EGFR-mutated non-small cell lung cancer, but acquired resistance emerges in most patients and remains a major barrier for complete cure." (PMID 41023502, 2025). "Non-small cell lung cancer (NSCLC) harboring epidermal growth factor receptor (EGFR) mutations have brought great challenges to the medical treatment in the world." (PMID 40142069, 2025). "Beyond EGFR mutations, clinically relevant genetic alterations in non-small cell lung cancer (NSCLC) include fusions involving ALK, ROS1, RET, and NTRK1/2/3." (PMID 41301039, 2025). "To date, three major and prevalent point mutations in EGFR, including L858R, T790M, and C797S, impact the use of TKIs in non-small cell lung cancer patients." (PMID 40649937, 2025).